CD4 (CD4 molecule)
Diseases named in the same sentence as CD4 in open-access papers (continued):
Sharing a sentence is not in itself a finding about the gene and the disease.
lymphopenia (continued). "Sex had only minor influence on CD4 T cell lymphopenia at lymphoid sites and CD4 T cell accumulation at mucosal sites." (PMID 24829607, 2014). "It has also been shown that the expansion of regulatory CD4+ T cells in response to lymphopenia is weaker than that of conventional CD4+ T cells in NOD mice." (PMID 24586733, 2014). "In summary we present an unusual case of L. infantum CL in a 76 year old Italian man with mild CD4 lymphopenia and a history of travel to an endemic area 19 years preceding presentation." (PMID 25428722, 2014). "As for CD4+ T-cells, relationships with viral load and CD4 lymphopenia were weaker, but still significant." (PMID 24803534, 2014). "We here present the first case of revertant mosaicism in JAK3 deficiency, manifesting as combined immunodeficiency evolving into predominant CD4+ lymphopenia." (PMID 25205547, 2014). "This Treg enrichment is the direct result of HIV-1 Nef expression in CD4+ T-cells, occurs independently of Nef-induced lymphopenia, and involves multiple mechanisms: lower apoptosis, enhanced cell division, and increased generation from precursors." (PMID 25344377, 2014). "We next evaluated the contributions of in vivo lymphopenia (CD4 T cell counts) and serum levels of IL-7 to t-STAT1 expression and activation (p-STAT1) in patients with chronic HIV infection." (PMID 24603698, 2014). "As a consequence, Cd4-Cre mediated Pak2 deletion results in severe T cell lymphopenia due to Pak2's multiple roles in T cell maturation and timed egress of thymocytes." (PMID 24843022, 2014). "Both lymphopenia and viral load contribute to the immune activation observed in the CD4 T cell pool." (PMID 24603698, 2014). "Only one sister (patient 2) showed CD4 lymphopenia on initial determination that improved during follow-up and IgG2-IgG4-subclass deficiency, while generation of selective polysaccharide antibodies was intact." (PMID 25205547, 2014). "As expected, hematologic toxicity was frequent in both groups with all patients experiencing grade 3–4 leucopenia and CD4 T-cell lymphopenia." (PMID 24726012, 2014). "T-cell specific Pak2 deletion using Lck-Cre or Cd4-Cre transgenes resulted in severe T cell lymphopenia." (PMID 24843022, 2014). "Taken together, these results indicate that, in the setting of HIV infection, CD4 T cell lymphopenia can contribute to upregulating t-STAT1 expression in CD4 T cells and this subsequently leads to increased levels of p-STAT1 following exposure to IFN-α." (PMID 24603698, 2014). "Pneumocystis jirovecii pneumonia (PJP) is infrequently reported in idiopathic CD4+ lymphocytopenia (ICL) patients." (PMID 28663813, 2014). "We here sought to determine the underlying molecular cause in an index family with two patients suffering from combined immunodeficiency that evolved into predominant CD4+ lymphopenia." (PMID 25205547, 2014). "CD4+ T cell-lymphopenia was either induced by anti-CD4 antibody-mediated cell depletion or by genetic deficiency of the major histocompatibility (MHC) class II transactivator (CIITA) in CIITA−/− mice." (PMID 24466045, 2014). "A significantly lower count of CD4+ cells with TLR9 was observed in patients with lymphopenia, compared with patients with a normal lymphocyte count (>1000/mm3) in the peripheral blood (4.59% ± 5.83 versus 6.86% ± 6.83 resp., P < 0.005)." (PMID 24692849, 2014). "Lymphopenia-induced proliferation is a mechanism triggered to maintain the CD4 T cell pool at a relatively constant size." (PMID 24603698, 2014). "This developmental block associated with reduced total numbers of DP and mature CD4+ and CD8+ SP thymocytes and peripheral lymphopenia (unpublished results)." (PMID 24465914, 2014). "We found that chemotherapy induces lymphopenia and that a significantly higher numbers of naïve CD4+ T cells and lower proportion of Treg before chemotherapy are associated with disease control after dacarbazine treatment." (PMID 25170840, 2014).
lymphopenia (continued). "Because CD4 T cells are under continuous homeostatic pressure, we hypothesized that these outcomes could be associated with differences in homeostatic regulation of these two pools and in their response to the combination of cytokines associated with lymphopenia and viral replication." (PMID 24603698, 2014). "IL-7 in vitro and lymphopenia in vivo differentially regulated expression of t-STATs in CD4 and CD8 T cells as well as their responses to Type-I IFN." (PMID 24603698, 2014). "In tumor studies, high levels of costimulation with OX-40/OX-40L, 4-1BB or costimulation in conjunction with lymphopenia induce a subset of CD4 CTL that express high levels of the T-box transcription factor, Eomes." (PMID 24586481, 2014). "Using bone marrow (BM) chimeras, we excluded that this is due the effects of lymphopenia; poor CD4+ T cell help; exhaustion, or altered cytokine receptor expression." (PMID 25385531, 2014). "Given that CD28 and IL-2 play important roles in Treg function, the relationships between premature CD4+ T cell aging and lymphopenia as well as Treg defects in autoimmune-prone NOD mice are proposed." (PMID 24586733, 2014). "We next compared the capability of lymphopenia-induced proliferation between pre-RTEs and lymph node-resident CD4+ naïve T cells." (PMID 23409179, 2013). "Expression of the activation marker HLA-DR correlated with TSLP responses, suggesting that lymphopenia-driven immune activation increased the sensitivity of CD4+ T cells to TSLP." (PMID 23383227, 2013). "Clinical symptoms and parameters, such as parotid enlargement, palpable purpura, low C4 levels, and especially CD4+ T lymphocytopenia, are valuable indicators of lymphoma development." (PMID 23853604, 2013). "To achieve CD4+ T-cell–restricted lymphopenia, we treated thymectomized animals with a low dose of anti-CD4 antibody." (PMID 24115907, 2013). "To distinguish between altered thymic development and lymphopenia as cause of the autoinflammation, we assessed the influence that different lymphopenic conditions had on the behaviour of TR2-deficient CD4+ T cells." (PMID 24115907, 2013). "In conclusion, we found a high proportion of CD4 cell lymphocytopenia in Ethiopian HIV-negative adults diagnosed with TB." (PMID 24358268, 2013). "In contrast to HIV+/TB, HIV-/TB patients with low CD4 cell counts had normal CD4 cell percentage, suggesting that the observed decreases in absolute CD4 cell counts are related to peripheral blood lymphocytopenia." (PMID 24358268, 2013). "The increase of circulating IL-7 in ICL patients parallels that seen in HIV-infected patients with severely depleted CD4+ T cell counts, and likely reflects a compensatory mechanism that promotes homeostatic T cell proliferation in response to lymphopenia." (PMID 23383227, 2013). "In all patients, CD4 + lymphocytes counts were monitored: 18.5 % of patients developed grade 3–4 CD4 + lymphopenia (<200 cell/μL)." (PMID 23703296, 2013). "In this study, lymphopenia and low CD4+ counts were observed in both patients who developed serious pneumonia." (PMID 22325903, 2012). "This patient not only had lymphocytopenia but more specifically a dramatic low CD4- (T-helper) cell count of 72/μl." (PMID 22747665, 2012). "During measles there is lymphopenia, but this is transient and changes in the proportions of CD4+ and CD8+ T cells in circulation are modest." (PMID 23029357, 2012). "Lymphopenia was significantly more common in severe illness and CD4 and NK cells were the major subsets contributing to lymphopenia, with no detectable B cell involvement." (PMID 22363665, 2012). "Multivariate analysis showed that marked CD4 lymphopenia (CD4<50 cells/μL) and severe anemia (as defined above) were each independently associated with NTS BSI (median CD4 among patients with NTS infection was 46 cells/μL)." (PMID 22761767, 2012). "Lymphopenia affects mostly CD4 T cells and especially naïve CD4 T cells, while CD8 T cells become relatively expanded." (PMID 22826712, 2012).
lymphopenia (continued). "In 25 patients, CD4+ lymphocytes counts were monitored; 14 (56%) of these patients developed a grade 3 CD4+ lymphopenia (<0.2*109/l) and 6 (24%) of these patients developed a grade 4 CD4+ lymphopenia (<0.05*109/l)." (PMID 22396071, 2012). "This lends further support to the observed relative lymphopenia and reduced CD4+ T cell numbers in PD found here and previously." (PMID 23054369, 2012). "Clearly, patients who receive ddTMZ are at risk to develop Pneumocystis carinii pneumonia, and prophylaxis is indicated in patients who develop lymphopenia or low CD4+ counts." (PMID 22396071, 2012). "Quantitative abnormalities in T cells have been described in the peripheral blood of patients with sarcoidosis with significant lymphopenia, involving CD4, CD8, and CD19 positive cells, common in sarcoidosis patients and correlating with disease severity." (PMID 22984568, 2012). "Together, these data strongly suggest that the CD4 T cell lymphopenia observed in BNm rats results from a disruption of the Themis gene and that the BNm rat thus represents a spontaneous Themis knock-out rat model." (PMID 22275874, 2012). "This patient’s CD4+ count was reduced, but Legionellosis is known to cause lymphopenia in the acute setting, so the role of HIV-induced lymphopenia as a risk-factor for Legionella infection in this context is unclear." (PMID 22998348, 2012). "Our findings demonstrated a reduction in circulating innate (NK and DC) and adaptive (CD4+) immune cells in samples obtained at enrollment, consistent with reports demonstrating significant lymphopenia and cell death early in the course of disease." (PMID 22742734, 2012). "We observed neutrophilia and CD4+ T lymphopenia in the acute phase of infection, followed by proliferation of CD8+ T cells during the convalescent phase." (PMID 22905277, 2012). "In another study, they were also able to identify a direct link between CD4 lymphopenia, febrile neutropenia, and early death after cytotoxic chemotherapy." (PMID 22383042, 2012). "Further experiments will be needed to determine if our model can sustain the viral replication beyond 120 day despite dramatic CD4 lymphopenia." (PMID 22675567, 2012). "Two of the patients with a grade 4 CD4+ lymphopenia developed a pneumocystis carinii pneumonia, prior to routine monitoring of CD4+ counts, from which they fully recovered." (PMID 22396071, 2012). "Lymphocytopenia (CD4 and CD8) was consistently observed in subjects who received a daily Fludarabine dose of 10 mg/m2 and higher." (PMID 22402597, 2012). "In the current study lymphocyte subset counts were also performed, which clearly show that lymphopenia is predominantly attributable to CD4 and NK cell depletion." (PMID 22363665, 2012). "By demonstrating highest LPS-dependant HLA-DR+ T-cells exclusively in patients with lowest CD4+ recovery, our findings add up to the consolidated bulk of evidence on the inverse correlation between HLA-DR expression and CD4+ lymphopenia." (PMID 22400042, 2012). "Linkage analysis and genetic dissection of the CD4 T cell lymphopenia in rats issued from BNm×DA crosses allowed the localization of the mutation on chromosome 1, within a 1.5 megabase interval." (PMID 22275874, 2012). "Nevertheless, a dramatic CD4 lymphopenia occurred at day 45 in all treated animals while CD8+ T cell loss only occurred in high dose treated animals." (PMID 23021024, 2012). "Compared to CMV-seropositive healthy individuals, ESRD patients have a significantly (P < 0.01) lower number of T lymphocytes which is related to a relative CD4+ T cell lymphopenia at all ages." (PMID 21214947, 2011). "The HAART therapy was continued with undetectable viral load but a persistent CD4 lymphopenia (50/mm3)." (PMID 22054169, 2011). "According to the best of our knowledge, we believe that this report is the first report to document the CD4 lymphopenia in Chikungunya with opportunistic Candidiasis infection." (PMID 20205786, 2010).
lymphopenia (continued). "Lymphocyte phenotyping shows CD4 lymphopenia with increased CD8 numbers resulting in a reversed CD4/CD8 ratio." (PMID 20465788, 2010). "With his lymphocyte count ranging between 120 and 1077 lymphocytes per microliter, however, it is possible that he had transient CD4+ lymphocytopenia." (PMID 20920200, 2010). "CD4 lymphopenia was marked with a CD4 count of 100/μl and a CD4:CD8 ratio of 0.16 at admission, which is lower than previously reported for any H5N1 case." (PMID 20540811, 2010). "Significant lymphopenia involving CD4, CD8, and CD19 positive cells was common in sarcoidosis patients and correlated with disease severity." (PMID 20140091, 2010). "Importantly, we observed markedly decreased expression of the major T-cell costimulatory molecule CD28 on both CD8 and CD4 T cells which together with the marked CD4 lymphopenia could be causal factors in the inadequate cell-mediated immune responses that frequently complicate the course of TB." (PMID 22567259, 2010). "In contrast to the CD8+, CD4+ T and NKT lymphopenia, DENV-2 infection caused significant increase in the number of NK cells (CD3–DX5+), macrophages (CD11b+F4/80+) and neutrophils (CD11b+Ly6G+)." (PMID 21206747, 2010). "Our experience with Chikungunya also showed lymphopenia with a decrease in the CD4 lymphocyte count level." (PMID 20205786, 2010). "Lymphopenia and inverted CD4/CD8 ratio were observed in our case and this can explain the extensive and huge ulcers and affection in the early infancy." (PMID 19126205, 2009). "The method of extrapolation of CD4 cell percentage based on absolute CD4 cell count risks misclassification of children with lymphopenia or lymphocytosis." (PMID 19390690, 2009). "Blood count and immunological study were normal except for the presence of lymphopenia and inverted CD4/CD8 ratio." (PMID 19126205, 2009). "As anticipated, this period of relative CD4 lymphopenia was accompanied by an elevation in IL-7 and IL-15 plasma levels (compared to baseline pre-infusion levels)." (PMID 19270751, 2009). "The aim of our study was to compare phenotypic and functional patterns of T-cells in ASCT recipients and in HIV-infected subjects, with comparable CD4+ lymphopenia but with starkly contrasting infectious risks." (PMID 18974880, 2008). "Ten age-matched subjects with comparable CD4+ lymphopenia were recruited: 5 cancer patients receiving ASCT 9 months before observation (ASCT) and 5 HIV+ antiretroviral naïve subjects (HIV)." (PMID 18974880, 2008). "Early severe sepsis is characterized by CD4-lymphopenia and increased NK cells, providing a survival benefit for the septic patient at percentages >20%." (PMID 17129388, 2006). "The present study provided evidence for the first time that early severe sepsis is characterized by CD4-lymphopenia and an increased presence of NK cells, providing a survival benefit for the septic patient at percentages >20%." (PMID 17129388, 2006). "The present study is the first to report the very early occurrence of CD4-lymphopenia in severe sepsis." (PMID 17129388, 2006). "This study aimed to investigate the dynamics of endogenous plasma levels of IL-7 during sepsis and septic shock, correlating its levels with lymphopenia and various lymphocyte subtypes, including CD4+ and CD8+ T cells, B cells, and natural killer T cells (NKT), in both survivors and non-survivors." (PMID 40005375, 2025). "Consequently, fingolimod therapy often leads to lymphopenia with CD4+ lymphocytes preferentially affected." (PMID 40548133, 2025). "Consistent with findings from virulent Armenia2008 and CADC_HN09 infection of outbred pigs, we observed lymphopenia, which could be attributed to the loss of CD3+CD4+CD8α− and CD3+CD4+CD8α− T-and CD21+ B cells." (PMID 41510007, 2025). "Lymphopenia was recovered with higher CD4 and CD8+ counts (a-MSC)." (PMID 40868058, 2025).
lymphopenia (continued). "Lymphopenia occurs in approximately one-third of patients, low B-cell or elevated transitional B cells are frequent, and T-cell profiles often show a reduction in CD4+ cells with an inverted CD4/CD8 ratio." (PMID 40370432, 2025). "Moreover, certain hematological alterations like CD4 lymphopenia, neutropenia, thrombocytopenia, anemia and thrombocytosis were predominant only in PTB patients and not in PTB with HIV." (PMID 40005523, 2025). "A substantially higher incidence is observed in those exposed to mAb or high-dose corticosteroids under contemporary treatment protocols, particularly among individuals with persistent CD4+ lymphopenia–a marker of impaired immune reconstitution that warrants prolonged monitoring." (PMID 41179870, 2025). "Furthermore, coinfection leads to severe lymphopenia in peripheral blood, resulting in reduced total IgG levels, neutralizing antibody titers, and CD4+ T cell responses to each virus." (PMID 40333344, 2025). "The lymphopenia of CD4+ T cells may be attributed to fluoride exposure restricting T subsets proliferation and promotes apoptosis." (PMID 40756359, 2025). "Importantly, the Themis KO model is characterized by lymphopenia affecting both CD4+ and CD8+ T cells." (PMID 41282140, 2025). "Recipients identified as high-risk–specifically those exposed to T-cell-depleting monoclonal antibodies or prolonged high-dose corticosteroids, and those with persistent lymphopenia (particularly CD4+ count < 200 cells/μL)–require extended and proactive ophthalmologic surveillance for 9–12 months." (PMID 41179870, 2025). "This is also true for the association with splenomegaly, as this is readily identified by ultrasound and also associated with multiple other already established cell markers in CVID diagnostics, such as lymphopenia, low naïve CD4 T cells, and expansion of CD21low B cells." (PMID 40496855, 2025). "Interestingly, in a competitive lymphopenia-induced homeostasis model, cKO CD4+ T cells exhibited a homeostatic proliferation defect at late but not early time points, but to a much lesser extent than that reported in CD8+ T cells." (PMID 40777021, 2025). "To date, experimental proof is still lacking to demonstrate that concomitant CD4+/CD8+ lymphopenia represents a common pathogenic pathway in CMV retinitis." (PMID 41179870, 2025). "However, lymphopenia was more pronounced in WT-infected mice as evidenced by lower CD4+ and CD8+ T cell counts compared to T209L DENV-infected mice." (PMID 40962941, 2025). "We describe a rare pediatric case of severe oral candidiasis caused by Candida parapsilosis (C. parapsilosis), associated with significant CD4+ lymphopenia and negative HIV serology." (PMID 40786310, 2025). "However, SARS-CoV-2 infection disrupts immune homeostasis, leading to lymphopenia and reduced CD4+ T-cell responses, which can impair MTB control and increase the risk of reactivation." (PMID 40283612, 2025). "CD3+ and CD4+ lymphopenia was observed in most examined patients." (PMID 41141376, 2025). "Notably, patients undergoing HD showed the highest level of immunosenescence, marked by lymphopenia, a lower CD4/CD8 ratio, and the expansion of pro-inflammatory monocyte subsets." (PMID 41153657, 2025). "Finally, a high percentage of monocytes and macrophages and a low percentage of CD8 T cells (concomitantly high CD4:CD8 ratio, r = 0.3, P = 0.0087) at baseline were found to be associated with prolonged lymphopenia after CAR‐T." (PMID 41368079, 2025). "P1 CD4+ T cells were modestly elevated in line with CD8+ T lymphopenia." (PMID 40295428, 2025). "The first reported case of a patient with PML treated with OCR and without prior DMT was a 78-year-old male who had received OCR for 2 years Lymphocyte test revealed grade 2 lymphopenia (780/μL), with a CD4+ count of 294/μL (normal range: 325–1,251/μL) and CD8+ count of 85/μL (90–775/μL)." (PMID 40308763, 2025).